PARP1 (poly(ADP-ribose) polymerase 1)
Diseases named in the same sentence as PARP1 in open-access papers (continued):
Sharing a sentence is not in itself a finding about the gene and the disease.
colitis (continued). "It is therefore not surprising that PARP-1 is involved in diseases sharing inflammatory/immune-mediated pathways, such as arthritis, diabetes, neurodegenerative disorders, colitis, and others, some of which are also linked to cancer development." (PMID 31877876, 2019). "Thus, in this context, PARP-1 plays a double role: by fueling inflammation, it promotes colitis and possible cancer progression; on the other hand, it contributes to genome stability, and therefore, cancer prevention (see also above)." (PMID 31877876, 2019). "On the contrary, inhibition of poly(ADP-ribosyl)ation preserves the cellular energy pool, thus preventing metabolic failure and providing cytoprotection, and previous in vivo studies demonstrated that genetic ablation of PARP-1 ameliorates the pathophysiological changes of experimental colitis." (PMID 23209735, 2012). "Recent studies in a variety of rodent models of experimental colitis by using PJ-34, a potent poly (ADP-ribose) polymerase-1 (PARP-1) inhibitor, support the concept that the marked beneficial effect of PJ-34 can be exploited to treat human inflammatory diseases." (PMID 20204057, 2009). "We further investigated whether restoration of Stc1 and Parp1 aggravated murine colitis." (PMID 38088577, 2024). "Finally, there is evidence for a boost of PARylation mediated by PARP1 in autoimmune (e.g. systemic lupus erythematosus) and inflammatory diseases (e.g. colitis), as well as in human atherosclerotic plaques, microvessels and lymphocytes of type 2 diabetic patients." (PMID 30991935, 2019). "To recover Stc1 and Parp1 expression, we intraperitoneally injected Stc1INT‐KO mice with AAV and induced colitis with DSS three weeks later." (PMID 38088577, 2024). "Hence, targeting STC1 and PARP1 might be a potential therapy for the alleviation of colitis." (PMID 38088577, 2024). "PARP1−/− and WT mice (five animals per group) were treated with 3% dextran sodium sulphate (DSS for 7 days to induce severe colitis that was confirmed by macroscopic (animal weight, colon length, and clinical score) and microscopic (histology) endpoints." (PMID 37108260, 2023). "C57BL6/J wild type (WT) and PARP1−/− mice were treated with DSS to induce acute colitis, or with the DSS and PARP1 inhibitor, PJ34." (PMID 37108260, 2023). "Importantly, adeno‐associated virus‐mediated restoration of Stc1 and Parp1 expression exacerbated dextran sodium sulfate‐induced colitis in Stc1INT‐KO mice, confirming the pathological synergy between STC1 and PARP1 in vivo." (PMID 40904702, 2025). "Also, by restoring Stc1 and Parp1 expression, the observed resistance to DSS‐induced colitis in Stc1INT‐KO mice was abolished." (PMID 38088577, 2024). "In addition, we verified the upregulation of PARP1 protein in the colonic tissues of patients with CD and in DSS‐ and TNBS‐induced acute mice colitis models." (PMID 38088577, 2024). "Herein, the function of STC1 in colitis and stress‐induced parthanatos, a newly identified type of programmed necrotic cell death dependent on the activation of poly‐ADP ribose polymerase‐1 (PARP1) is investigated." (PMID 38088577, 2024). "While we found no decrease in the levels of NAD+-synthesizing enzymes within the intestinal epithelium of mice undergoing experimental colitis, we did find an increase in the mRNA level, as well as the enzymatic activity, of the NAD+-consuming enzyme poly(ADP-ribose) polymerase-1 (PARP1)." (PMID 37744380, 2023). "FK866, a small NAMPT inhibitor, reduces mucosal NAD+ and NAD+-dependent enzymes (including PARP1, SIRT6, and CD38), NF-κB pathway activation, and inflammatory cell infiltration, thereby improving DSS-induced colitis in mice and preventing inflammation-related tumors." (PMID 37371959, 2023). "Overall, these data highlight that the absence of PARP1 is protective against the onset of murine colitis." (PMID 37108260, 2023). "PARP1 and PARP2 have also been documented to promote colitis in mice." (PMID 35976971, 2022).
colitis (continued). "Moreover, genetic deficiency or pharmacological inhibition of PARP1 reduces colitis in rodents; however, no study has assessed the link between PARP1 and NAD+ levels during colitis." (PMID 37744380, 2023). "However, PARP1(-/-) mice were not prone to tumor formation, and transcriptomic analysis showed that the mice were protected from colitis." (PMID 36982223, 2023). "The beneficial effect of PARP1 inhibition was also confirmed in various animal models including dinitrobenzene sulfonic acid (DNBS) and trinitrobenzene sulfonic acid (TNBS) induced acute and chronic colitis and spontaneous chronic colitis developed in IL-10 knockout mice." (PMID 37457706, 2023). "Our findings suggest that activation of PARP1 may be primarily responsible for the depletion in cellular NAD+ stores and eventual mitochondrial dysfunction that occurs within the intestinal epithelium during colitis." (PMID 37744380, 2023). "Interestingly, NR treatment did not reduce the activity of PARP1 in DSS colitis, as evidenced by similar levels of pADPr-modified proteins in the intestinal epithelium of DSS+Vehicle versus DSS+NR mice, but NR did unexpectedly reduce pADPr-modified protein levels in Citrobacter-infected mice." (PMID 37744380, 2023). "Inhibition of the nuclear enzyme PARP-1 may reduce the apoptotic process by shifting the ratio of apoptotic regulators along with reduction of JNK activity, and beneficial effects of inhibitors of this nuclear polymerase have been reported in experimental models of colitis." (PMID 23209735, 2012).
myocardial infarction (16 papers, 2009 to 2025). Gross necrosis of the myocardium, as a result of interruption of the blood supply to the area, as in coronary thrombosis. "PARP-1 inhibitors have been used in phase 1 clinical trials in humans with ST-Segment elevation myocardial infarction." (PMID 39337409, 2024). "PARP1 activation was previously observed in the nuclei of cardiomyocytes after transplantation and in mononuclear cells from patients with myocardial infarction, as well as in septic shock patients with myocarditis." (PMID 35740913, 2022). "Also, the administration of PARP-1 inhibitors to rats was cardioprotective in postischemic reperfusion, reducing the size of myocardial infarction." (PMID 39337409, 2024). "Increased activation of PARP-1 was observed in rodents after myocardial infarction." (PMID 39337409, 2024). "We then investigated the effects of PARP1 and autophagy in mice myocardial infarction (MI)." (PMID 30323296, 2018). "Our data for the first time suggests that inhibition of PARP1 is novel potential strategy against autophagy, might reduce the permanent damage to cardiomyocytes, such as ischemic heart disease or myocardial infarction." (PMID 30323296, 2018). "Furthermore, exosomes originating from pericardial WAT mitigate post-myocardial infarction through adipsin-mediated regulation of iron homeostasis, while adipsin sourced from epicardial WAT contributes to cardiomyocyte apoptosis after myocardial infarction via mediation of PARP-1 activity." (PMID 39538244, 2024). "To test the effect of exogenous PARP1 on cardiac injury in adult animals, we generated myocardial infarction model and intramyocardially injected AAV9-PARP1 into adult WT mice." (PMID 38481797, 2024). "Recent studies have proved that PARP1 inhibition can protect diabetic heart via activating SIRT1-PGC1 alpha axis; Through activating SIRT1-induced inhibition of PARP1, post myocardial infarction infammation and cardiac remodeling can be prevented." (PMID 34124031, 2021). "In cardiac regeneration models, CPT1 inhibition reverses metabolic reprogramming and reduces PARP1‐mediated DUSP1 PARylation, leading to decreased p38 mitogen‐activated protein kinase (MAPK) phosphorylation and activation of adult cardiomyocyte proliferation post‐myocardial infarction." (PMID 40904702, 2025).
brain tumors (14 papers, 2011 to 2024). "Present study was designed to explore the possible involvement of PARP1 gene polymorphisms in brain tumor." (PMID 31609976, 2019). "Heterozygous mutant genotype of second selected SNP of PARP1 gene rs1805414, showed protective effect against the brain tumor risk in Pakistani population." (PMID 31609976, 2019). "Further studies on other functional PARP1 SNPs are needed to define the role of the PARP1 gene polymorphisms in brain tumor." (PMID 31609976, 2019). "Selected SNPs of PARP1 gene were linked with the overall risk of brain tumor mutant allele of rs1136410 and rs1805404 SNPs were found involved in increased risk of brain tumor." (PMID 31609976, 2019). "Additionally, the frequency of genotypes of selected PARP1 polymorphisms was also correlated with different types and grades of the brain tumor in order to further illuminate the role of these polymorphism in brain tumorigenesis." (PMID 31609976, 2019). "Firstly, a large sample size in the future studies (with various ethnic backgrounds) may be used to further confirm the association between SNPs of PARP-1 gene and brain tumor susceptibility." (PMID 31609976, 2019). "Association of PARP1 gene polymorphisms and different parameters of brain tumor." (PMID 31609976, 2019). "The PARP1 combined genotyping SNPs findings proved statistically significant in brain tumor cases compared with controls." (PMID 31609976, 2019). "Here we show that PARP1 is expressed in high grade pediatric brain tumors, thereby indicating the rationale of PARP1 as a potential therapeutic target in these cancers." (PMID 22184287, 2011). "A recent study indicated the high expression of PARP1 in pediatric brain tumors, showing a significantly higher PARP1 mRNA and protein expression in high-grade pediatric brain tumors, compared to their low-grade counterparts." (PMID 22184287, 2011). "In all pediatric brain tumor cell lines used in this study, strong PARP1 protein expression was demonstrated by Western Blot." (PMID 22184287, 2011). "Defects in DSB repair in pediatric brain tumors, providing rationale of synthetic lethality with PARP1 inhibition are to be explored." (PMID 22184287, 2011). "We examined PARP1 protein expression in different pediatric brain tumor cell lines by Western Blot analysis." (PMID 22184287, 2011). "In fact, olaparib is blood brain barrier (BBB) penetrant and could serve as an effective brain tumor therapy Considering the genomic instability of CGNPs following PARP1 and ATR ablation, there is also a potential for synergism between PARP and ATR inhibition." (PMID 35747808, 2022). "Further analysis showed negative association for selected polymorphisms of PARP1 gene with other parameters such as age, gender, IR and types of brain tumors." (PMID 31609976, 2019). "Cells with heterozygous PARP-1 may have a wider range of molecular specificity for base excision repair, therefore preventing the tumorigenesis of brain tumors more effectively." (PMID 31609976, 2019). "However, limited number of studies have been reported with respect to PARP-1 gene SNP analysis and brain tumors." (PMID 31609976, 2019). "Distribution of frequency of PARP-1 SNPs in brain tumor patients and controls." (PMID 31609976, 2019). "Notably, brain tumors also exhibit a similar upregulation of PARP1." (PMID 39598347, 2024). "The unique combination of PARP1 selectivity, trapping profile, and high CNS penetration positions AZD9574 as a best-in-class PARP inhibitor for treating primary and secondary brain tumors." (PMID 39399414, 2024).
brain tumors (continued). "Although subtypes of cells in non-neoplastic brain region showed some PARP1 positivity, an abundant and profusely intensive nuclear PARP1 staining was observed in tissues of pediatric brain tumors, especially HGG and ependymoma." (PMID 22184287, 2011). "In silico analysis of PARP1 mRNA expression revealed higher PARP1 expression in pediatric brain tumors compared to non-malignant brain." (PMID 22184287, 2011). "As a validation of the gene expression data, we assessed PARP1 protein expression by immunohistochemistry in high grade pediatric brain tumors and tissues derived from non-malignant pediatric brain." (PMID 22184287, 2011).
endothelial dysfunction (14 papers, 2009 to 2026). In vascular diseases, endothelial dysfunction is a systemic pathological state of the endothelium (the inner lining of blood vessels) and can be broadly defined as an imbalance between vasodilating and vasoconstricting substances produced by (or acting on) the endothelium. "ONOO− increase is associated with a reduced PARP-1 pathway which contributes to the endothelial dysfunction." (PMID 33204398, 2020). "Recent evidence indicated that PARP1 gene deletion was associated with maintenance of eNOS activity against dyslipidemia-induced endothelial dysfunction." (PMID 30158868, 2018). "Emerging evidence shows PARP1 associated with maintenance of eNOS activity and dyslipidemia-induced endothelial dysfunction." (PMID 30158868, 2018). "Of note, PARP1 gene deficiency normalized the high-cholesterol-diet–induced NO reduction and endothelial dysfunction in mice, possibly by maintaining eNOS activity." (PMID 30158868, 2018). "The protective effect of PARP-1 gene deletion against dyslipidemia-induced endothelial dysfunction was associated with preservation of eNOS activity." (PMID 19823587, 2009). "This may induce the vascular failure caused by a PARP-1 decrease that contributes to endothelial dysfunction." (PMID 32486343, 2020). "Because both high glucose and Ang II can activate PARP1 and cause endothelial dysfunction, we cultured HUVECs under high glucose or Ang II with or without AICAR to examine whether activation of AMPK can inhibit PARP1 activation and consequent PARylation." (PMID 26986624, 2016). "Maintenance of eNOS activity may be associated with the protective effect of PARP-1 gene deletion against dyslipidemia-induced endothelial dysfunction." (PMID 19823587, 2009). "Numerous studies of PARP-1 involvement in oxidative stress-associated endothelial dysfunction, primarily using cell culture and ex vivo systems, have demonstrated that pharmacological inhibition of PARP-1 confers protection against such dysfunction (for review)." (PMID 19823587, 2009). "Therefore, it is tempting to speculate that the ability of PARP-1 deficiency to prevent such extensive oxidative stress and to maintain eNOS activity underlies protection against endothelial dysfunction and dysregulated autonomic nervous system." (PMID 19823587, 2009). "Inhibition of PARP1 has been shown to protect against age‐related endothelial dysfunction in both cerebromicrovascular and cardiovascular systems." (PMID 41310943, 2026). "Several studies have reported that extensive PARP1 activation contributes to maintaining vascular inflammation and endothelial dysfunction." (PMID 36829935, 2023). "We revealed a novel mechanism through which PARP1 mediates oxLDL-enhanced arginase II expression and contributes to endothelial dysfunction." (PMID 30158868, 2018). "A growing body of data demonstrates intermittent or long term modulation of PARP-1 activity attenuates the severity of endothelial dysfunction and even capable to reverse these processes." (PMID 28339485, 2017). "This decrease in miR-223 expression was regulated by increased activity of hypoxia-inducible factor 1α (HIF1α), and this in turn upregulated PARP-1 activity and contributed to endothelial dysfunction." (PMID 28660007, 2017). "Taken together, the data presented here suggest biguanides and ARBs have a beneficial effect on the vasculature by the cascade of AMPK phosphorylation of PARP1 to inhibit PARP1 activity and protein PARylation in ECs, thereby mitigating endothelial dysfunction." (PMID 26986624, 2016). "In order to establish the role of PARP-1 in endothelial dysfunction in conscious mice, the present study determined whether PARP-1 gene deletion provides protection against endothelium-dependent (acetylcholine; ACh) and independent (sodium nitroprusside; SNP) vasodilators." (PMID 19823587, 2009).
endothelial dysfunction (continued). "In conclusion, the present work provides experimental evidence that Sanguis draconis (SD) could suppress high glucose-induced endothelial dysfunction and oxidative stress via inhibition of ERK/NF-κB/PARP-1 activation in primary cultured HUVEC." (PMID 24987732, 2014).
Hypertension (14 papers, 2012 to 2025). The presence of chronic increased pressure in the systemic arterial system. "Given that miR-103a-2-5p and miR-585-5p are both predicted to target PARP1, and PARP-1 has previously been implicated in hypertension pathology, we examined whether miR-103a-2-5p and miR-585-5p regulate PARP-1 expression." (PMID 28660007, 2017). "The complete pathway of PARP1 regulation will need to be further examined to understand its role in hypertension disparities." (PMID 28660007, 2017). "In the context of racial differences in hypertension, we observed higher levels of PARP1 in AAHT compared to AANT." (PMID 28660007, 2017). "Although we validated this functional interaction in endothelial cells, to what degree miR-585-5p regulates PARP1 expression in PBMCs and how that contributes to hypertension etiology remains to be elucidated." (PMID 28660007, 2017). "However, from the viewpoint of the side effect, PARP1 inhibitors are still less acceptable to patients with hypertension." (PMID 29738496, 2018). "Furthermore, we identified that the hypertension-related miRNAs in PBMCs, miR-103a-2-5p and miR-585-5p, target PARP1 in endothelial cells." (PMID 28660007, 2017). "Here, we have identified that PARP1 is differentially expressed with hypertension and race." (PMID 28660007, 2017). "Thirty-two weeks of pharmacological PARP-1 inhibition by L-2286 treatment attenuated hypertension induced structural and functional alterations of carotid arteries by a lowered level of oxidative damage and an interference with stress related inflammatory and cell death propagating signaling events." (PMID 28339485, 2017). "Therefore, we cannot exclude that these other miRNAs, such as miR-223, may play a role in targeting PARP-1 expression in hypertension." (PMID 28660007, 2017). "In addition, PARP-1 activity and binding to DNA repair proteins are also altered with age which may also be relevant considering hypertension increases with age." (PMID 28660007, 2017). "Many other cellular processes also rely on PARP-1 signaling, and abnormal PARP-1 activity has been attributed to various age-related diseases, including hypertension." (PMID 28660007, 2017). "However, we did not observe any significant changes in these miRNAs with race or hypertension status in our previous study, which indicates that in this context, miR-103a-2-5p and miR-585-5p have roles in systemic arterial hypertension physiology in PARP-1 regulation." (PMID 28660007, 2017). "Here, we found that the poly-(ADP-ribose) polymerase 1 (PARP-1), a DNA damage sensor protein involved in DNA repair and other cellular processes, is upregulated in AA women with hypertension." (PMID 28660007, 2017). "Here we raise the possibility in which inhibition of PARP-1 could be beneficial in this scenario and this hypothesis was tested in SHR animals on the hypertension induced oxidative damage of carotid vessels and neuronal tissue." (PMID 28339485, 2017). "However, differential expression of PARP-1 has not been investigated with respect to health disparities in essential hypertension." (PMID 28660007, 2017).